RNU4-90P (RNA, U4 small nuclear 90, pseudogene)
Gene: Small nuclear RNA gene on chromosome 5 (91,270,727 to 91,270,867, forward strand). Ensembl gene ENSG00000199643.
Homologues: Orthologues: chimpanzee U4 (99% identical), macaque U4 (96% identical). Paralogues in human: RNU4-49P (79% identical), RNU4-10P (74% identical), RNU4-36P (72% identical), RNU4-81P (72% identical), RNU4-32P (70% identical), RNU4-15P (70% identical), RNU4-17P (68% identical), RNU4-28P (68% identical), RNU4-51P (67% identical), RNU4-50P (67% identical), RNU4-53P (63% identical), RNU4-24P (62% identical), and 81 more.